BACE1 (beta-secretase 1)
Diseases named in the same sentence as BACE1 in open-access papers (continued):
Sharing a sentence is not in itself a finding about the gene and the disease.
diabetes (47 papers, 2012 to 2025). "These enzymes are linked to diabetes-induced neurodegeneration by driving processes such as cholinergic deficiency (AChE), amyloid plaque formation (BACE-1), inflammation and oxidative stress (DPP-4), and tau pathology (GSK-3β)." (PMID 39766390, 2024). "BACE1 has been linked to insulin signalling and leptin signalling, and has been implicated in the development of diabetes." (PMID 35562959, 2022). "Diabetes has displayed an increased risk of AD by 50% by influencing Aβ pathology by NF-κB upregulation and independent overexpression of beta-site amyloid precursor protein cleaving enzyme 1 (BACE1)." (PMID 35327563, 2022). "The phenotype of the BACE1 knockout mice models, including reduced weight gain, hypomyelination, and associations with metabolic diseases such as diabetes, proposes a physiological role of BACE1 in energy metabolism and homeostasis." (PMID 35119166, 2022). "The β-site amyloid precursor protein cleavage enzyme 1 (BACE1) is associated with increased amyloidogenesis, and has been affiliated with diabetes via its role in metabolic regulation." (PMID 32867761, 2020). "Here, we demonstrate that the major amyloidogenic enzyme, BACE1, is sufficient to increase the risk of diabetes development when expressed in neurons only." (PMID 27138913, 2016). "In conclusion, the results presented here demonstrate that STZ-induced insulin-deficient diabetes exacerbates Aβ accumulation by elevating expression levels of the β-secretase enzyme BACE1 and its substrate APP in the 5XFAD mouse model of AD." (PMID 22403710, 2012). "Consistently, under the high-fat diet (HFD) which causes obesity and diabetes, BACE1 knockout could improve glucose metabolism of mice and protect mice from obesity." (PMID 40507910, 2025). "Moreover, the BACE1 gene polymorphism has been associated with the risk of diabetes in PIMA Indians." (PMID 36585686, 2022). "Our findings suggest that BACE1 inhibitors may have therapeutic value in the treatment of vascular disease associated with diabetes." (PMID 32407295, 2020). "The results also suggest that translational mechanisms through phosphorylation of eukaryotic initiation factor-2α (eIF2α) may underlie the upregulation of BACE1 associated with insulin-deficient diabetes." (PMID 22403710, 2012). "In conclusion, dysregulation of miR-146a/miR-9/NF-κB-dependent inflammatory signaling and followed by enhancement expression levels of the AβPP, BACE1, and the ratio of Bax to Bcl-2 in the hippocampus may be an underlying mechanism in diabetes-related memory impairment." (PMID 32934245, 2020). "In this study, we observed significant increases in BACE1 level and enzyme activity in the liver of WT-HFD mice, indicating the involvement of BACE1 in obesity-induced diabetes." (PMID 40507910, 2025). "Taken together, our results provide further evidence of the BACE1-induced disruption on the InsR-signaling pathway in diabetes, and indicate that BACE1 is involved in the pathologies of diabetes mellitus." (PMID 40507910, 2025). "Previous research discovered that impaired insulin receptor signaling contributed to insulin resistance of diabetes mellitus, and BACE1 was identified to regulate the InsR level in HUBC mice." (PMID 40507910, 2025). "According to histopathological studies, rats with STZ-induced diabetes present decreases in the mean myelin content (BACE1 levels) and the myelin/axon ratio, an increased endoneurial space, and reductions in the conduction velocity and pain thresholds." (PMID 39139674, 2024). "This presents an important metabolic role for BACE1 and highlights BACE1 as a potential therapeutic target for the treatment of obesity induced diabetes." (PMID 35119166, 2022). "The amount of biologically active full-length INSR in the liver is reduced during diabetes, which can be partially restored with the presentation of BACE1 inhibitors." (PMID 33947097, 2021).
diabetes (continued). "In summary, we characterized the sequence of events leading to the cleavage of IR by BACE1 in the liver during diabetes." (PMID 34029592, 2021). "The cleavage of the insulin receptor by β-secretase 1 (BACE1) in the liver increases during diabetes, which contributes to reduce insulin receptor levels and impair insulin signaling." (PMID 34029592, 2021). "Our results indicated that hyperglycemia interestingly induced the upregulation of both AβPP and BACE1 mRNA expression levels that confirmed a common link between diabetes and cognitive dysfunction." (PMID 32934245, 2020). "In this connection, they suggested that insulin signaling can be improved with the use of BACE1 inhibitors during diabetes." (PMID 32993632, 2020). "In STZ treated group (Diabetes control), the expression of BACE1, PSEN1, APAF1, CASPASE3, and CATALASE genes were upregulated in the cerebral cortex of the rat brain as compared to the untreated group (Vehicle control)." (PMID 33737876, 2020). "This flavonoid was responsible for the antioxidant activities and inhibitory activities against the key enzymes controlling diabetes (α-glucosidase and α-amylase) and AD (AChE, BChE, and BACE-1)." (PMID 32887386, 2020). "In this line, previous studies suggested that diabetes or IR can stimulate Aβ accumulation via NF‐κβ induction and AβPP and BACE1 overexpression." (PMID 32934245, 2020). "We demonstrate that the IR ectodomain is cleaved by BACE1, that this cleavage occurs in the liver and increased during diabetes, thus decreasing the amount of mature IR." (PMID 29610518, 2018). "During diabetes, BACE1-dependent cleavage of IR is increased and the amount of IR in the liver is reduced, whereas infusion of a BACE1 inhibitor partially restores liver IR." (PMID 29610518, 2018). "Recently, global Bace1 deletion was shown to protect against diet-induced obesity and diabetes, suggesting that BACE1 is a potential regulator of glucose homeostasis." (PMID 27138913, 2016). "In the present study, we investigated the effect of high glucose on BACE1 expression and related mechanisms by using in vivo and in vitro, Zucker Diabetic Fatty (ZDF) rats and SK-N-MC human neuroblastoma cells, respectively." (PMID 27829662, 2016). "Our data suggest that a HF diet induces diabetes mellitus (DM)-like metabolism in ApoE4 mice, as well as changes in β-site amyloid precursor protein-cleaving enzyme 1 (BACE1) protein levels between the two ApoE strains." (PMID 27656136, 2016). "Much of the difference is due to BACE1 being a younger target since the protein was only identified in 1999 (although a consensus on the target concept for DPPIV in diabetes only emerged a couple of years before this)." (PMID 24204758, 2013). "In addition, C. maxima albedo extract exhibited wide ranges of inhibitory properties against enzymes, which are drug targets for the treatment of AD (AChE, BChE, and BACE-1), obesity (lipase), and diabetes (α-glucosidase and α-amylase)." (PMID 37241861, 2023). "Neuronal human BACE1 knock-in in mice induced systemic diabetes." (PMID 36585686, 2022). "Accordingly, BACE1 knock‐in mice display an AD‐like pathology including elevated levels of Aβ plaques, synaptic impairments, decreased cognitive function, and systemic diabetes." (PMID 35119166, 2022). "Increased BACE1 levels and activity are observed in AD, as well as other diseases associated with an increased risk of AD, such as diabetes; however, the mechanisms are not entirely clear." (PMID 35562959, 2022). "Furthermore, BACE1 has important physiological roles, one of which is related to cleavage of the insulin receptor and neuronal BACE1 knock-in induces systemic diabetes in mice." (PMID 35248531, 2022). "Mechanisms that regulate the cleavage of IR by BACE1 in the liver during diabetes may constitute targets to improve insulin sensitivity." (PMID 34029592, 2021). "BACE1-dependent cleavage of INSR in the liver is increased during diabetes." (PMID 33947097, 2021).
diabetes (continued). "The purpose of this study was to elucidate the mechanisms that regulate BACE1-dependent cleavage of IR during diabetes to identify regulatory steps that could be pharmacologically targeted to reduce IR cleavage and improve insulin sensitivity." (PMID 34029592, 2021). "BACE1 inhibition restores functional cell-surface IR and increases insulin signaling, supporting the use of BACE1 inhibitors to improve liver insulin signaling during diabetes." (PMID 29610518, 2018). "In summary, our data demonstrate for the first time that IR is a novel substrate for BACE1 and that therapies targeting BACE1 inhibition could be an innovative treatment for diabetes and other diseases characterized by insulin resistance." (PMID 29610518, 2018). "Treatment of db/db mice with C3 increases hepatic levels of the mature form of IR, while remaining below (approximately half) of those of the control mice, indicating that BACE1 activity is involved in the reduction of liver IR expression that occurs during diabetes." (PMID 29610518, 2018). "We suggest the potential use of BACE1 inhibitors to enhance insulin signaling during diabetes." (PMID 29610518, 2018). "Nevertheless, during diabetes the BACE1-dependent cleavage of liver IR, by reducing hepatic insulin sensitivity, may also contribute to peripheral metabolic disorder." (PMID 29610518, 2018). "Furthermore, our results suggest that BACE1 inhibition could be a potential therapeutic target for diabetes mellitus through the restoration of insulin-signaling dysfunction." (PMID 40507910, 2025). "Given the extent of research into effective BACE1 inhibitors for AD, the repurposing of BACE1 inhibitory drugs for treatment of metabolic syndromes such as diabetes and obesity, or as a dual therapy against both diseases, could be a huge advancement in the treatment of metabolic disorders." (PMID 35119166, 2022). "In a model of diabetes-induced memory impairment, it has been observed the upregulation of the expression levels of miR-146a, miR-9, TNF-α, NF–kB, and subsequently amyloid-β protein precursor (AβPP), beta-site APP cleaving enzyme 1 (BACE1), and BCL2 associated X, apoptosis regulator (Bax)." (PMID 33923599, 2021). "Taken together, our findings provide a mechanistic foundation for a link between diabetes and AD by demonstrating that insulin deficiency may change APP processing to favor β-amyloidogenesis via the translational upregulation of BACE1 in combination with elevations in its substrate, APP." (PMID 22403710, 2012). "Thus, alterations in BACE1 levels may be involved in the pathophysiology of diabetes." (PMID 36585686, 2022). "This study investigated phenolics, especially isoflavones, and inhibitory activities against the key enzymes relevant to the control of obesity (lipase), diabetes (α-amylase, α-glucosidase and DPP-IV) and AD (AChE, BChE and BACE-1)." (PMID 36496713, 2022). "Results indicate that diabetes significantly upregulated the expression levels of miR-146a, miR-9, TNF-α, NF-κB, and subsequently AβPP, BACE1, and Bax." (PMID 32934245, 2020). "A potential role for BACE1 in metabolic regulation has only recently emerged, as Bace1 knockout improved glucose metabolism and protected mice from HFD-induced obesity and diabetes." (PMID 27138913, 2016). "In the brain of a rat model of diabetes, activation of RAGE with AGEs leads to NF-κB-dependent expression of BACE1." (PMID 22482078, 2012). "To further investigate whether inhibiting BACE1 could enhance insulin sensitivity and alleviate symptoms of diabetes, we treated HFD mice with the BACE1 inhibitor Elenbecestat." (PMID 40507910, 2025). "However, we took in consideration several potential confounders (age, gender, hypertension, diabetes, CVD, etc.)and the observed increase in BACE1 activity was independent from those factors." (PMID 32917964, 2020).
diabetes (continued). "However, the expression of App and Ps1 in the PFC was not significantly affected by diabetes, while Bace1 expression was significantly lower in db/db mice (two-way ANOVA, p < 0.05)." (PMID 41228412, 2025). "However, BACE1 mRNA levels were not significantly affected by STZ treatments in 5XFAD mice, suggesting that transcriptional mechanisms may not account for the BACE1 elevation associated with insulin-deficient diabetes." (PMID 22403710, 2012).
memory impairment (27 papers, 2010 to 2025). "IL-33 may ameliorate D-gal–induced aging bone loss and memory impairment in mice by regulating IL-17, Tregs, BACE1 expression, and tau phosphorylation, thereby inhibiting inflammaging." (PMID 39224568, 2024). "Additionally, APP overexpressing transgenic mice that also lack the BACE1 gene are devoid of cerebral Aβ, amyloid deposition, and Aβ-associated memory impairments." (PMID 25621019, 2014). "Herein, SCO/HMM administration produced memory impairment and forms of Aβ plaque, increasing BACE1 levels in rat brains." (PMID 40325262, 2025). "ApoE4 Female: displays earlier onset of spatial and memory impairment, ↑ Aβ species, BACE1 and Sp1, and ↑ BACE1 expression." (PMID 39126053, 2024). "In light of these evidences, rationally it can be proposed that IL-33 attenuates memory impairment through its intrinsic property to inhibit BACE-1 expression and tau phosphorylation." (PMID 39224568, 2024). "Improves spatial learning ability and memory impairment; reduces levels of Aβ1-42 and BACE-1; prevents hyperphosphorylation of tau." (PMID 39149548, 2024). "Studies showed that BACE1 and MAOA proteins are strongly linked to aging-associated memory impairment." (PMID 35767571, 2022). "Opposite to the down-regulation of GSTA1, GSTO1, and KEAP1, the BACE1 and MAOA proteins are elevated during the aging-associated memory impairment." (PMID 35767571, 2022). "The 3NCP alleviates memory impairment, reduced plaque formation, and inhibits BACE-1 activity, displaying activities comparable or higher than the reported drugs such as melatonin, quercetin, and rutin." (PMID 34502467, 2021). "Secondly, ECH dramatically decreased cerebral Aβ production and accumulation by inhibiting the translation of BACE1, and significantly ameliorated memory impairment in 2 × Tg-AD mice." (PMID 33330477, 2020). "While these drugs show promise, there are potential complications from a possible role in synaptic function and increased memory impairment and seizures in BACE-1 –/– mice." (PMID 27199640, 2016). "These type 2 DM models show increased levels of Aβ and the β-secretase-cleaved C-terminal fragment of APP (β-CTF or C99, an intermediate β-metabolite of APP) concomitant with BACE1 elevations in the hippocampus and cerebral cortex, leading to learning and memory impairments." (PMID 41446639, 2025). "Moreover, friedelin administration improved neuronal synapse and reversed scopolamine-induced memory impairment accompanied by the inhibition of β-secretase enzyme (BACE-1) to halt amyloidogenic pathways of amyloid-β production." (PMID 35889382, 2022). "Thus, the present study investigated the effects of EA on memory impairment, Aβ production, and BACE1 expression in senescence-accelerated mouse prone 8 (SAMP8) mice." (PMID 26283960, 2015). "To compare efficacies of BACE1+/− deletion in improving memory impairments in 5XFAD transgenic mice at 6 and 15–18 months of age, we tested the mice with a hippocampus-dependent learning paradigm, spontaneous alternation in the Y-maze that represents a measure of spatial working memory." (PMID 20886088, 2010). "Crocin treatment improved memory impairment and attenuated the gene expression of HIF‐1α and BACE1 in the brains of neonate rat." (PMID 33586916, 2021). "In this model, BACE1 elevation facilitated β-amyloidogenic processing of APP as measured by increased levels of β-CTF and the β-secretase-cleaved soluble ectodomain of APP (sAPP-β) and decreased sAPP-α, leading to aggravated learning and memory impairment." (PMID 41446639, 2025). "In conclusion, mahanimbine could protect learning and memory impairment in aged mice through attenuation of oxidative stress (MDA), deposition of Aβ1-42, AChE level, and BACE-1 activity while increasing antioxidant (GSH) and ACh levels." (PMID 35053756, 2021).
memory impairment (continued). "Insulin resistance increases key enzymes that produce Aβ and phosphorylate tau, such as BACE1, γ-secretase and GSK3 β, while it reduces levels of key enzymes that degrade Aβ, such as IDE, accompanied by oxidative stress, which damages synaptic remodeling and ultimately leads to memory impairment." (PMID 31178714, 2019).